NLRP3 (NLR family pyrin domain containing 3)
Diseases named in the same sentence as NLRP3 in open-access papers (continued):
Sharing a sentence is not in itself a finding about the gene and the disease.
infectious mononucleosis (1 paper, 2024). A condition characterized by an increase in mononuclear white blood cells and swollen lymph nodes, which is usually caused by infection with the Epstein-Barr virus. "Ebv-induced infectious mononucleosis results in elevated levels of IL-18 in plasma and maintains the expression of EBV-dissolving switch ZEBRA via NLRP3, thus promoting the replication and release of virions." (PMID 38590522, 2024).
Interstitial pneumonitis (1 paper, 2021). "Our in vivo studies demonstrated that gefitinib administration via oropharyngeal aspiration caused lung inflammation, which was inhibited by MCC950, suggesting the involvement of the NLRP3 inflammasome in gefitinib-induced interstitial pneumonitis." (PMID 33414419, 2021). "Thus, our findings demonstrate that the NLRP3 inflammasome plays a key role in the induction of lung inflammation such as interstitial pneumonitis triggered by gefitinib." (PMID 33414419, 2021).
intestinal tumour (1 paper, 2017). "Our results show that PsV eradicates intestinal tumours of ApcMin/+ mice via activating the NLRP3 and AIM2 inflammasomes, leading to caspase-1-mediated tumour regression." (PMID 28397782, 2017). "Although normal epithelial cells express both NLRP3 and AIM2 innate immune receptors, we observed significant pyroptosis primarily in intestinal tumour cells but not normal epithelial cells." (PMID 28397782, 2017).
intraductal papillary mucinous neoplasm (1 paper, 2021). "This murine model mechanistically showed NLRP3-regulated IL-18-induced eosinophil accumulation and degranulation, merged pancreatic ducts, pancreatic intraepithelial neoplasia 1 (PanIN1), PanIN2, PanIN3, and intraductal papillary mucinous neoplasm (IPMN)." (PMID 34183442, 2021).
intraepithelial neoplasia (1 paper, 2017). A precancerous neoplastic process that affects the squamous, glandular, or transitional cell epithelium without evidence of invasion. "The comparative analysis between adjacent benign, intraepithelial neoplasia (PIN) and malignant tissues for NLRP3 or NLRP12 is from the same slide of cancerous tissue." (PMID 28663562, 2017).
ischemic optic neuropathy (1 paper, 2021). "However, overactivated microglia provide excessive amounts of the inflammatory ligands IL-6, IL-1β, and TNF-α, causing ROS, iNOS, NFκB, and NLRP3 inflammatory complex activation; additionally, disruption of neuronal homeostasis was observed in ischemic optic neuropathy." (PMID 34573098, 2021).
laryngeal carcinoma (1 paper, 2022). Carcinoma that arises from the laryngeal epithelium. "Further investigation revealed that RGMB-AS1 silencing inhibits laryngeal cancer cell proliferation and invasion, and suppressed in vivo tumor growth, thorough miR-22 sponging and increasing NLRP3 expression." (PMID 35406495, 2022).
lepromatous leprosy (1 paper, 2020). A chronic communicable infection which is a principal or polar form of leprosy. "NLRP3 is overexpressed in lepromatous leprosy - Theimmunohistochemical data presented in Fig. 1shows that samples from LL/BL had intense or moderate intensity of NLRP3." (PMID 32130367, 2020). "NLRP3 inflammasome’s immunohistochemical strong expression score is ahallmark of the Lepromatous Leprosy - The immunohistochemicalexpression of NLRP3, caspase-1, caspases-4/5, IL-1β, IL-6, and IL-18 between thegroups presented statistically significant differences in the scores." (PMID 32130367, 2020).
limb girdle muscular dystrophy type 2B (1 paper, 2021). "Various studies have demonstrated that the NLRP3 inflammasome triggers a pathogenic inflammatory response in many inherited myopathies, including limb girdle muscular dystrophy type 2B (LGMD2B), valosin-containing protein (VCP) associated diseases, and Duchene muscular dystrophy (DMD)." (PMID 34831246, 2021).
Lipedema (1 paper, 2025). Disorder of adipose tissue characterized by symmetric and bilateral enlargement of the lower extremities due to abnormal deposition of subcutaneous fat often in obese women. "The suppression of CFD observed in lipedema may prevent full ACP activation, resulting in sublytic MAC production, NLRP3 inflammasome priming, and downstream alterations in immune signaling without overt cytotoxicity." (PMID 41185844, 2025).
Liver abscess (1 paper, 2021). A circumscribed area of pus or necrotic debris in the liver. "Real-time quantitative polymerase chain reaction (qPCR) was conducted to detect expression levels of NLRP3 inflammasome-related genes in liver abscess tissue." (PMID 34659265, 2021).
lung adenoma (1 paper, 2019). A benign, well circumscribed epithelial neoplasm that arises from the bronchus or the lung parenchyma. "Moreover, NLRP3−/− mice treated with B(a)p or B(a)p plus LPS also mainly developed lung adenoma with 92.9% and 87.5%, respectively." (PMID 30696442, 2019).
Lysosomal disease (1 paper, 2020). "Although we did not test many other combinations, the likelihood is that whether a substrate is primary or secondary is irrelevant for stimulation of NLRP3 inflammasome activation, suggesting that NLRP3 and IL‐1 secretion will have an impact in most neuronopathic lysosomal diseases." (PMID 32057196, 2020).
meningioma (1 paper, 2025). A generally slow growing tumor attached to the dura mater. "Differences in the expression of genes relating to innate immunity (such as NLRP3, IL-18 and IL-1B) between meningioma and VS were identified, with VS having a more immune-rich, inflammatory profile than meningioma overall." (PMID 41437121, 2025).
middle ear diseases (1 paper, 2021). "Regarding the potential role of inflammasomes in middle ear diseases, one experimental animal study revealed aberrant overexpression of NLRP3, ASC, caspase-1, and IL-1β in lipopolysaccharide-induced otitis media." (PMID 34805037, 2021).
middle ear infection (1 paper, 2024). "ELISA assays were then performed to test the protein levels of NLRP3 and its downstream factors at 7d after middle ear infection." (PMID 39277762, 2024). "Furthermore, we measured the protein level of the NLRP3 inflammasome using ELISA assays at 7d after middle ear infection." (PMID 39277762, 2024). "Prior to investigating how the depletion of cochlear resident macrophages or NLRP3 knockout condition affects the inner ear, we assessed whether these conditions affect the middle ear infection." (PMID 39277762, 2024). "The data revealed that neither macrophage depletion nor NLRP3 deletion significantly affects the development and burden of the CSOM middle ear infection." (PMID 39277762, 2024). "Their mRNA expression was found to be significantly elevated in CSOM (42.1 ± 13.3 for NLRP3, 199.2 ± 73.4 for IL-1β) compared to control (non-CSOM) cochleae (1.91 ± 0.91, p = 0.018 for NLRP3; 2.83 ± 1.55, p = 0.032 for IL-1β) at 7 days following middle ear infection." (PMID 39277762, 2024).
mucocutaneous leishmaniasis (1 paper, 2025). The most common form of leishmaniasis that is transmitted through the bite of female phlebotomine sand flies or after exposure to leishmania parasites. "In particular, the high densities of NLRP3+, AIM-2+, and IL-1β+ cells found in the hyperreactive form of the disease suggest a role in exacerbating the inflammatory response in patients with mucocutaneous leishmaniasis (MCL)." (PMID 40431153, 2025).
multiple acyl-CoA dehydrogenase deficiency (1 paper, 2022). "In a 2018 study, Chokchaiwong and colleagues investigate the ability of CoQ10 to restore mitochondrial function, and to prevent oxidative damages and NLRP3 activation in multiple acyl-CoA dehydrogenase deficiency (MADD), an autosomal recessive disorder that causes mitochondrial dysfunction." (PMID 35563625, 2022).
Mycoplasma infections (1 paper, 2023). "In line with this notion, CIAS1 7 unit repeat genetic polymorphism in NLRP3 has been associated with decreased IL-1β levels and increased occurrence of vaginal Candida and Mycoplasma infections." (PMID 36611990, 2023).
myelofibrosis (1 paper, 2023). A partial or complete replacement of the bone marrow stroma by fibrous tissue. "Through regulation of the miRNA rs2431697 genotype and NLRP3, NF-κB1, and IL-1β genes, new therapeutic strategies could be considered to prevent myelofibrosis progression in MPN patients." (PMID 36902299, 2023).
nematode infection (1 paper, 2018). "Finally, we determined whether the inflammatory responsiveness of Nlrp3 and Il1b is influenced in vivo by nematode infection triggered alternative macrophage activation." (PMID 29343442, 2018).
Neurodegeneration (1 paper, 2018). Progressive loss of neural cells and tissue. "It is well recognized that the activation of NLRP3 inflammasomes is an indicator for the development of neurodegeneration diseases and also a pre-requisite for neuroinflammation initiation." (PMID 30232232, 2018).
neuroendocrine carcinoma (1 paper, 2025). A malignant neuroendocrine neoplasm composed of cells containing secretory granules that stain positive for NSE and chromogranin. "Still G3 neuroendocrine carcinoma (NEC) are poorly differentiated and show lower expression of CgA, which may affect the Nlrp3/miR-223-related effect described here." (PMID 39851539, 2025).
nodular melanoma (1 paper, 2018). "In particular the presence of nodular melanoma (NM) was associated with NLRP3-rs35829419 and NLRP1-rs12150220." (PMID 30447690, 2018).
non-melanoma skin carcinoma (1 paper, 2021). "We have shown how TAK-242 highly effective in preventing UVB-induced non-melanoma skin cancer in mice by the repair of UVB-induced DNA damage and inactivation of NLRP3 inflammasome in the skin." (PMID 34771569, 2021).
obesity syndrome (1 paper, 2020). "To evaluate the contribution of the NLRP3 inflammasome and its downstream effectors IL-1 and IL-18 in this process, we applied the true-to-life “American lifestyle-induced obesity syndrome” (ALiOS) diet mouse model." (PMID 33202693, 2020).
ocular hypertension (1 paper, 2021). Abnormally high intraocular pressure. "To understand the underlying mechanism of PM2.5-related ocular hypertension, we measured the levels of proteins associated with the classic pyroptosis pathway (NLRP3/caspase-1/IL-1β/GSDMD) in aqueous humor outflow tissue." (PMID 33663554, 2021).
oral mucositis (1 paper, 2014). Inflammation of the mucous membranes of any of the structures in the mouth. "In the present study, we looked at whether the NLRP3 inflammasome pathway is involved in 5-FU-induced Sa3 cell death with the ultimate goal of developing effective strategies to prevent or treat oral mucositis." (PMID 25389767, 2014). "We also looked at whether Kampo formulation Daiokanzoto (TJ-84) has a beneficial effect on oral mucositis by affecting the biological processes induced by 5-FU such as cell death, mitochondrial dysfunction, ROS generation, and NLRP3 inflammasome activation." (PMID 25389767, 2014).
osteosclerosis (1 paper, 2022). Abnormally high bone density. "Cartilage destruction and subchondral osteosclerosis were found in OA patients and OA model rats, and the expression level of NLRP3 was significantly increased in synovial tissue, which indicates that NLRP3 inflammasome was involved in the pathogenesis of OA." (PMID 36042519, 2022).
ototoxicity (1 paper, 2025). damage to the ear, specifically the cochlea or auditory nerve as a result of some toxic stimulus, eg from a drug. "More recently, we also compared the otoprotective effects of the antioxidant rosmarinic acid and the anti-inflammatory drug anakinra in suppressing NLRP3 activation in a model of styrene-induced ototoxicity (unpublished data)." (PMID 41324731, 2025).
Paraproteinemia (1 paper, 2020). An abnormal immunoglobulin or part of an Ig (light chain) in the circulation. "We used two disease controls, WM since these patients have IgM paraprotein, but no overt inflammatory complications, and NLRP3-AID, a SAID that clinically resembles SchS, but with no paraproteinemia." (PMID 33424831, 2020).
parasite (1 paper, 2018). "THP-1 cells that lacked caspase-1 or NLRP3 were severely defective in IL-1β production in the parasite infections." (PMID 30301855, 2018).
partial seizures (1 paper, 2017). "Therefore, the aim of this present study was to investigate the role of NLRP1 (rs8079034, rs878329), NLRP3 (rs4612666, rs10754558, and rs2027432), and P2X7R (rs3751143, rs208294) gene polymorphisms in Chinese partial seizures population." (PMID 28503575, 2017).
perinatal disease (1 paper, 2022). A condition affecting an unborn or newly born individual, where the perinatal period is defined in humans as commencing at 22 completed weeks (154 days) of gestation and ending seven completed days after birth. "Recently, interest has been piqued in exploiting the NLRP3 inflammasome pathway as a potential chemotherapeutic strategy to ameliorate the risk associated with perinatal disease outcomes." (PMID 36409087, 2022).
pertussis (1 paper, 2013). A contagious bacterial respiratory infection caused by Bordetella pertussis. "pertussis immunity in Pa-immunized Nlrp3−/− mice, we found a dramatic reduction in the rate of bacterial clearance in Pa-immunized IL-1RI−/− mice, with 1000 fold more bacteria in the lungs when compared with Pa-immunized WT mice at 3 and 7 days post challenge." (PMID 23592988, 2013).
placental disorders (1 paper, 2020). "Similarly, the NLRP3 inflammasome inhibitor glibenclamide also decreases inflammasome activation in human trophoblasts, thus highlighting the therapeutic potential of the NLRP3 inflammasome for the treatment of placental disorders." (PMID 32047476, 2020).
placental insufficiency (1 paper, 2021). Failure of the placenta to deliver an adequate supply of nutrients and oxygen to the fetus. "Knockdown of NR4A2 under hypoxia significantly increased expression of NLR family pyrin domain containing 3 (NLRP3), a master regulator of the inflammasome (p = 0.0065) and Serine Peptidase Inhibitor, Kunitz Type 1 (SPINT1), associated with placental insufficiency (p = 0.0056)." (PMID 34667209, 2021).
plague (1 paper, 2015). Plague is a severe bacterial infection caused by the gram-negative bacterium Yersinia pestis. "To identify the host mediators of inflammasome activation during pneumonic plague, we examined IL-1β production and Y. pestis virulence within the lungs of NLRP3-/-, NLRC4-/- and wild-type mice." (PMID 25781467, 2015).
Plasmodium vivax malaria (1 paper, 2019). Malaria resulting from infection by Plasmodium vivax. "NLRP3 has consistently been implicated as a sensor for inflammasome activation in monocytes from both P. falciparum and Plasmodium vivax malaria patients." (PMID 31265218, 2019).
Pneumocystis infections (1 paper, 2024). "Although previous studies had questioned their significance in Pneumocystis infections and the clearance of Pneumocystis, our results indicate that neutrophils may contribute to the host’s inflammatory response by initiating NLRP3-inflammasome assembly and undergoing NETosis." (PMID 38953359, 2024).
polyp (1 paper, 2025). A usually exophytic mass attached to the underlying tissue by a broad base or a thin stalk. "Compared to that in normal mucosal tissues, the ratio of positively stained areas for NLRP3, apoptosis-associated speck-like proteins containing a caspase recruitment domain, and interleukin-1β was higher in polyp tissues." (PMID 40520898, 2025). "Our results showed that, compared to that in normal mucosal tissues, the ratio of positively stained areas for NLRP3, ASC, and IL-1β increased in polyp tissues." (PMID 40520898, 2025).
postmenopausal osteoporosis (1 paper, 2024). Metabolic disorder associated with fractures of the femoral neck, vertebrae, and distal forearm. "Rationale: NLRP3 inflammasome is critical in the development and progression of many metabolic diseases driven by chronic inflammation, but its effect on the pathology of postmenopausal osteoporosis (PMOP) remains poorly understood." (PMID 38994035, 2024).
primary progressive MS (1 paper, 2025). "Likewise, PBMCs from patients with primary progressive MS (PPMS) overexpress pro-inflammatory cytokines, including IL-1β, IL-6, TNF, and NLRP3, with monocytes being the primary driver of this profile." (PMID 40710307, 2025).
protein (1 paper, 2022). "More importantly, NF-κB/MAPK-mediated activation of NLRP3 inflammasome may be a target for adjuvant treatment of SEA toxin protein infection in the future." (PMID 35051006, 2022).
ptosis (1 paper, 2020). The drooping of the upper eyelid. "AIM2 and NLRP3 act as sensors to take part in the activation of caspase-1, which catalyzes neuroinflammation and ptosis." (PMID 32377306, 2020).
pulmonary regurgitation (1 paper, 2025). "This study aimed to investigate the role of turbulent shear stress (TSS) induced by pulmonary regurgitation (PR) in driving right ventricular (RV) dysfunction, with a focus on NLRP3 inflammasome activation, inflammation, and fibrosis, particularly in the RV outflow tract (RVOT)." (PMID 40384971, 2025).
reactive depression (1 paper, 2022). "Tests of between-subjects effects showed that the NLRP3 expression in the reactive depression group was significantly different among the three groups (F = 3.666, P = 0.030) and the size of the effect reported medium effect size (ηp2 = 0.089)." (PMID 35295780, 2022). "Pairwise comparisons showed that the expression of NLRP3 in the reactive depression group was significant lower than that of the other two groups." (PMID 35295780, 2022). "Significantly, the value of the serum NLRP3 level of the reactive depression group was most likely to occur around 3.2 ng/ml." (PMID 35295780, 2022). "Our findings suggested the serum NLRP3 and BDNF levels could be potential biomarkers for detecting and evaluating the severity of reactive depression." (PMID 35295780, 2022). "Hence, the serum NLRP3 and BDNF levels could be potential biomarkers for detecting and evaluating the severity of reactive depression." (PMID 35295780, 2022).
renal dysfunction (1 paper, 2019). "Significantly higher renal tubular NLRP3 expression levels were detected in patients with severe renal dysfunction (eGFR < 60 ml/min/1.73 m2) than in patients with less severe renal dysfunction (eGFR ≥ 60 ml/min/1.73 m2) (0.042 ± 0.0171 vs 0.029 ± 0.0112, P = 0.034)." (PMID 31796125, 2019).
Respiratory tract infection (1 paper, 2016). An infection of the upper or lower respiratory tract. "Of noteworthy interest is the up-regulation of IL-1β and NLRP3 in samples from children with the most severe respiratory tract infection." (PMID 27171557, 2016).
reticulum cell sarcoma (1 paper, 2023). An antiquated term that refers to a non-Hodgkin lymphoma composed of diffuse infiltrates of large, often anaplastic lymphocytes. "Compounds 154, 155, 157 and 158 from Callicarpa arborea showed potent inhibitory effects against the NLRP3 inflammasome by inhibiting Casp-1 activation and IL-1β in reticulum cell sarcoma cells." (PMID 37375299, 2023).
retinal dystrophies (1 paper, 2025). "Moreover, Nlrp3 knockout reduced spontaneous, age-related BLamDs in WT mice, suggesting translatability of our findings not only to rare inherited retinal dystrophies, but also potentially to AMD itself." (PMID 41198612, 2025). "Moreover, Nlrp3 knockout reduced the size and coverage of age-related BLamDs in a WT C57BL/6 background, suggesting translatability of our findings not only to rare inherited retinal dystrophies (ML/DHRD), but also potentially to sporadic AMD." (PMID 41198612, 2025).